ADGRG1 (adhesion G protein-coupled receptor G1)
Diseases named in the same sentence as ADGRG1 in open-access papers (continued):
Sharing a sentence is not in itself a finding about the gene and the disease.
Sepsis (1 paper, 2023). Sepsis is defined as life-threatening organ dysfunction caused by a dysregulated host response to infection. "Five characteristic genes—BCL2A1, CD44, ADGRG1, TGIF1, and ING3—were identified, which enabled the prediction of mortality of sepsis." (PMID 37069215, 2023).
tumor (52 papers, 2012 to 2026). "ADGRG1/GPR56, a representative tumor-associated aGPCR, is recognized as a potential biomarker/prognostic factor of specific cancer types with both tumor-suppressive and tumor-promoting functions." (PMID 34943858, 2021). "We find that ADGRG1 is specifically highly expressed in CD8+ tumor-reactive T cells compared to bystander T cells." (PMID 39243082, 2024). "We identify ADGRG1 as the specific marker of tumor antigen-experienced CD8+ T cell and validate it through the conditional mouse model." (PMID 39243082, 2024). "GPR56/ADGRG1 promotes the conversion of tumor cells into mesenchymal cells, contributing to tumor growth and metastasis via the PI3K/AKT pathway, and predicting a worse prognosis for patients with CRC." (PMID 38673975, 2024). "ADGRG1 (GPR56) is a representative tumor-related G protein-coupled receptors (GPCRs) member, which plays an important role in tumor cell growth, migration, angiogenesis, and metastasis." (PMID 38424222, 2024). "Particularly, we found that ADGRG1 had the highest proportion (74.90%) and was almost specifically expressed in tumor-reactive T cells." (PMID 39243082, 2024). "In summary, the results obtained from Runx1Runx1t1/+; Mx1-Cre mouse validated the specific role of ADGRG1 in tumor-reactive T cells of AML." (PMID 39243082, 2024). "The in vitro experiments such as the interferon-γ (IFN-γ) release assays and the cell-killing assay using AML samples also confirm the tumor-reactive property of ADGRG1+CD8+ T cells." (PMID 39243082, 2024). "The involvement of PARG in suppression of tumor angiogenesis is supported by the observation that, in contrast to its effect on many chemokine genes, hPARG expression upregulates ADGRG1 gene 8-fold." (PMID 35585513, 2022). "In this review article, we summarize the molecular and functional properties of ADGRG1/GPR56 and discuss its diverse roles in tumor progression." (PMID 34943858, 2021). "All these data suggested that the inhibition of ADGRG1 in SiHa suppressed tumor growth, but improved its sensitivity and reactivity to cisplatin in vivo." (PMID 34367958, 2021). "In conclusion, ADGRG1 mediates tumor-invasive growth and chemoresistance via PI3K/Akt/mTOR signaling pathway." (PMID 34367958, 2021). "In particular, 89% of Adgrg1+CD8+ T cells were tumor-reactive T cells." (PMID 39243082, 2024). "ADGRG1 can serve as a specific marker of CD8+ tumor-reactive T cells in AML BM." (PMID 39243082, 2024). "The Adgrg1, Pdcd1, Osgin1, Lag3, and Chn2 were predominantly expressed in tumor-reactive T cells." (PMID 39243082, 2024). "Moreover, a larger scale of analysis across different AML subtypes is needed to confirm the role of ADGRG1 in CD8+ tumor-reactive T cells." (PMID 39243082, 2024). "Though AML with RUNX1::RUNX1T1 patients were used as an example to explore, we also obtained consistent conclusions in other AML subtypes, suggesting that ADGRG1 could become a potential unified marker of CD8+ tumor-reactive T cells within AML." (PMID 39243082, 2024). "These suggested that the characteristic of ADGRG1 as a marker for tumor-reactive T cells not only presented in RUNX1::RUNX1T1 positive AML but also might be a common feature of tumor-reactive T cells in AML." (PMID 39243082, 2024). "We summarize herein the latest findings of the role of ADGRG1/GPR56 in tumor progression." (PMID 34943858, 2021). "Also, we recognized ADGRG1 as the specific marker of tumor-reactive T cells in AML." (PMID 39243082, 2024). "Together, our findings depict the single-cell profile of tumor-reactive T cells in AML BM and propose that ADGRG1 can act as an indicator of T cell tumor reactivity in AML, which may be further harnessed for adoptive cell therapy and tumor-reactive TCR enrichment." (PMID 39243082, 2024). "Thus, ADGRG1 may be further harnessed for adoptive cell therapy and tumor-reactive TCR enrichment in AML." (PMID 39243082, 2024).
tumor (continued). "Additionally, we found ADGRG1 could serve as the specific marker of CD8+ T tumor-reactive T cell and validated it through the Runx1Runx1t1/+; Mx1-Cre mouse model." (PMID 39243082, 2024). "Genes such as ADGRG1, TBX21, S1PR5, FCRL6, and FCGR3A showed relatively selective expression in tumor-reactive T cells (the average expression in bystander T cells < 0.5)." (PMID 39243082, 2024). "In cytotoxic NK cells, the expression of ADGRG1 is regulated by the transcriptional factor ZNF683, which has also been upregulated in the tumor-reactive T cells from AML." (PMID 39243082, 2024). "By drawing on experiences from solid tumor research, we identified tumor-reactive T cells with unique phenotypes in AML, especially AML with RUNX1::RUNX1T1, and detected ADGRG1 as their marker." (PMID 39243082, 2024). "GPR56/ADGRG1 is upregulated in CRC tissues and cell lines and promotes tumor growth and metastasis by inducing epithelial-to-mesenchymal transition." (PMID 36551877, 2022). "Upon antigen stimulation, it is possible that ADGRG1, as a member of the ZNF683 regulatory network, participates in the modulation of T cell effector function and NK transition, mediating the unique phenotype of AML tumor-reactive T cells." (PMID 39243082, 2024). "Thus, we observed an elevated expression of ADGRG1 specifically in T cells of AML, particularly in tumor-reactive T cells, suggesting its potential utility as a marker for tumor-reactive T cells." (PMID 39243082, 2024). "Meanwhile, we found that relapsed/refractory AML patients have fewer ADGRG1+CD8+ T cells at diagnosis, suggesting the lack of a robust anti-tumor immune response." (PMID 39243082, 2024).
cancer (43 papers, 2013 to 2025). A tumor composed of atypical neoplastic, often pleomorphic cells that invade other tissues. "ADGRG1 has been shown to participate in cancer-cell proliferation and associated with inferior results in AML." (PMID 37509244, 2023). "In BEN cells, which show the third-highest ADGRG1 level within the cancer cell line encyclopedia (portals.broadinstitute.org/ccle), we found >20 Ensembl-annotated ADGRG1 transcripts." (PMID 34944065, 2021). "To find an adherent cell line for knocking out high endogenous ADGRG1, we screened carcinoma-derived cell lines using flow cytometry." (PMID 34944065, 2021). "GPRs have been implicated in the development of diseases like cancer, one of these is the G Protein-Coupled Receptor 56 (GPR56) with 693 amino acid (aa) residues, encoded by Adhesion G-Protein Coupled Receptor G1 (ADGRG1) gene." (PMID 32856858, 2020). "Detailed in vitro and in vivo analyses further indicated that ADGRG1 is a prosurvival factor in cancer cells and promotes anchorage-independent growth whereas ADGRE5 and ADGRF5 regulate RhoA-dependent cell migration and invasion." (PMID 29468160, 2018). "In addition, Adhesion G Protein-Coupled Receptor G1 (ADGRD1) functions in cell matrix adhesion and cancer progression [reviewed in 52], and KITLG (SCF/c-Kit) encodes the cytokine that acts as the ligand for the tyrosine-kinase KIT receptor." (PMID 37276213, 2023). "The interaction between COL3A1 from fibroblasts and ADGRG1 from cancer cells might contribute to the BoM process and these findings are worth future validation through either in vitro or in vivo studies." (PMID 38187400, 2023). "The adhesion GPCR, ADGRG1 (GPR56), has been identified as a TG2 interaction partner in cancer invasion." (PMID 38397010, 2024). "G protein-coupled receptor 56 (GPR56/ADGRG1) is an adhesion GPCR with an essential role in brain development and cancer." (PMID 35600402, 2022). "Cancer cell lines originating from same organ often gathered in the same cluster, such as C2 [COAD/READ-STAD-PAAD], a group of digestive system cancers whose common features were the high expression of CNKSR1, FOLH1, ADGRG1, SMAD7, LRATD1 and MVP." (PMID 32874774, 2020).
infection (4 papers, 2012 to 2021). The state of being infected such as from the introduction of a foreign agent such as serum, vaccine, antigenic substance or organism. "We found that Adgrg1 was specifically upregulated in CD8+ TRM cells in the memory phase after infection with HSV or LCMV." (PMID 34685654, 2021). "The TRM cell-specific upregulation of Adgrg1 appeared to occur in the memory phase, given that we were unable to detect expression of Adgrg1 in effector populations, including terminal effector cells (TECs) and memory precursor effector cells (MPECs) at day 8 after infection with LCMV." (PMID 34685654, 2021).
neurodevelopmental disorder (2 papers, 2019 to 2021). A behavioral and cognitive disorder with onset during the developmental period that involves impaired or aberrant development of intellectual, motor, or social functions. "GPR56/ADGRG1 is an emerging member of the GPCR family with considerable therapeutic potential in neurodevelopmental disorders." (PMID 34803612, 2021).
ADGRG1 also shares sentences with these, for which no sentence is quoted: glioblastoma (12 papers); breast carcinoma (8); prostate carcinoma (5); dystroglycanopathies (4); esophageal cancer (4); ovarian carcinoma (4); Intellectual disability (3); metastatic melanoma (3); non-small cell lung carcinoma (3); Obesity (3); atherosclerosis (2); brain malformation (2); brain tumor (2); colon (2); Encephalopathy (2); esophageal squamous cell carcinoma (2); Glucose intolerance (2); hepatocellular carcinoma (2); metastatic disease (2); neurological diseases (2); pancreatic cancer (2); Usher syndrome (2); acute lymphoblastic leukemia (1); adenocarcinoma (1); adenoma (1); Alzheimer disease (1); anaplastic carcinomas (1); asthma (1); astrocytic tumor (1); autism (1).
A further 62 diseases each share a sentence with ADGRG1 in 1 paper.